IL6 (interleukin 6)
Diseases named in the same sentence as IL6 in open-access papers (continued):
Sharing a sentence is not in itself a finding about the gene and the disease.
diabetes (continued). "Three independent risk factors for hypoactive delirium were identified: diabetes mellitus (OR 3.305, 95% CI: 1.866–12.616; p = 0.047), CRP level (OR 1.002, 95% CI: 1.001–1.023; p = 0.044), and IL-6 level (OR 1.045, 95% CI: 1.017–1.063; p = 0.001)." (PMID 38523173, 2024). "Diabetes patients had increased levels of circulating IL-6 and trans-signaling co-receptors, and plasma sgp130 levels positively linked with HbA1c in both patient groups." (PMID 38535313, 2024). "The expressions of IL17A, MMP2, IL10 and IL6 are up-regulated with diabetes that promote the progression of OP, whereas the expressions of FGF2 and VEGFA are down-regulated." (PMID 38250601, 2024). "Interleukin 6 (IL-6) has been intensively studied regarding its role in the specific oxidative dynamics of diabetes." (PMID 39744134, 2024). "Diabetes-enhanced IL-17 stimulates the expression of other inflammatory mediators such as IL-6, IL-8, PGE2, TNF-α, and RANKL and can indirectly enhance osteoclastogenesis, thereby increasing periodontal tissue damage." (PMID 38614881, 2024). "Recent studies confirm the correlation between the level of IL-6 and the complications of diabetes, both in murine models and among young patients." (PMID 39744134, 2024). "Age, history of diabetes, history of chronic kidney disease, vaccination status, interleukin-6, procalcitonin, leukocytes, lymphocytes, and D-dimer were identified as predictors and used to develop a nomogram model to predict long COVID risk." (PMID 38822405, 2024). "Currently, the number of clinical trials investigating IL-6 inhibitors for diabetes treatment is limited." (PMID 39749325, 2024). "Further dissection between central and peripheral effects of the cytokine and distinct signaling modes is mandatory to carefully assess the therapeutic potential of IL-6 inhibiting agents in diabetes and DKD." (PMID 39723211, 2024). "The importance of the variables was obtained as follows: using the mean decrease in Gini as a criterion, neurological disease, diabetes, IL-6 levels and dexamethasone made the greatest contributions." (PMID 38616284, 2024). "The inflammation that occurs in adipose tissue due to the release of TNF-α, IL-1β, and IL-6 is a crucial factor in the development of cardiovascular disorders, diabetes, and cancers." (PMID 38317220, 2024). "In terms of heart rate, blood pressure, MCP-1, IL-6, and stress recovery, people with diabetes displayed reduced stress responses." (PMID 38333442, 2024). "In our investigation of IL6 and TNFα, we found that baseline IL6 levels were significantly lower in the cancer group compared to the control group, even when adjusted for BMI, diabetes, and parity." (PMID 38339282, 2024). "C-reactive protein (CRP) and interleukin-6 (IL-6) have been identified as strong predictors of both diabetes and CVD in prospective cohort studies." (PMID 39408364, 2024). "Increased plasma concentrations of IL-6 trans-signaling components show a clear correlation with HbA1c levels in patients with diabetes concomitant chronic liver disease." (PMID 39749325, 2024). "Elevated levels of high-sensitivity CRP, IL-6, and TNF-α were positively associated with the risk of microvascular complications in patients with diabetes." (PMID 39170741, 2024). "Systemic inflammation caused by pro-inflammatory cytokines in periodontitis like IL-6 and TNF-α contributes to cardiovascular disease, diabetes, and metabolic syndrome." (PMID 39795606, 2024). "Normoglycemic South Asian women had similar concentrations of hsCRP, IL-6, leptin and adiponectin as women with prediabetes or diabetes." (PMID 39097697, 2024). "IL-6 plays a role in stimulating the inflammatory and auto-immune processes in many conditions, including diabetes, cancer, and auto-immune diseases." (PMID 38786524, 2024).
diabetes (continued). "In conclusion, the idea of dividing the patients into smaller groups arose when we obtained highly elevated but very ununiform levels of IL-6 in the dialyzed patients, especially in those with diabetes." (PMID 38921685, 2024). "Conversely, age inversely affected IL-4 levels, and diabetes mellitus negatively influenced IL-6 levels." (PMID 39456722, 2024). "In diabetes induced animal model, the leaf extract reduced the circulatory levels of inflammatory markers such as Interleukin-1 beta (IL-1β), Interleukin 6 (IL-6), and TNF-α." (PMID 39479139, 2024). "Inflammation markers, including C-reactive protein (CRP), interleukin 6 (IL6), E-selectin, and soluble intercellular adhesion molecule 1 (sICAM-1), exert a function in diabetes development." (PMID 39339769, 2024). "In individuals with diabetes, MCs were found to secrete various cytokines such as IL-6 and IFN, along with chemokines like eotaxin, monocyte chemoattractant protein 1 (MCP-1), and RANTES." (PMID 38255949, 2024). "Gut microbiota metabolites primarily exert their therapeutic effects on diabetes through the IL6, AKT1, and PPARG targets." (PMID 39707185, 2024). "Diabetes is frequently associated with elevated levels of inflammatory cytokines (e.g., TNF-α, IL-1β, and IL-6) and AGEs, which have been linked to the pathophysiology of both diabetes and OA." (PMID 39139325, 2024). "Diabetes mellitus is considered as inflammatory disease due to presence of cytokines such as interleukin (IL)-6 and TNF-α which rose in the blood of diabetic patients." (PMID 38528644, 2024). "AKI analysis: A history of diabetes mellitus was associated with AKI in multiple logistic regression analysis, and the addition of preoperative IL-6 levels improved the prediction model for AKI occurrence (AUC 0.69 to AUC 0.74)." (PMID 39199217, 2024). "Although the results of other conducted studies are inconsistent, they indicate that mothers with pre-pregnancy diabetes show abnormal pro–inflammatory protein/cytokine concentrations, such as IL–8, IL–6, CRP, TNF–α and IFN–γ." (PMID 38308265, 2024). "Two, characterizing serum and plasma markers (resorption CTX, formation P1NP, sclerostin, insulin, insulin-like growth factor 1, IL-6, TNFα, etc.)would identify potential metabolic pathways by which diet and diabetes lower the fracture resistance of bone." (PMID 39012489, 2024). "Conversely, well-treated diabetes patients show lower IL-6 levels and a less severe grade of periodontitis." (PMID 38396821, 2024). "Diabetes was thereby affiliated with the M1 macrophages recruitment and the expression of IL-6 and IL-1B during the IRI procedure." (PMID 39656542, 2024). "Proinflammatory conditions produced by diabetes induce Interleukin-6 (IL-6), Tumor Necrosis Factor-α (TNF-α), and other chronic inflammatory markers." (PMID 38611003, 2024). "Although it is a pro-inflammatory cytokine, IL-6 seems to have a protective role in the pathogenesis of diabetes." (PMID 39744134, 2024). "Salivary interleukin-6, matrix metalloproteinase-8, and osteoprotegerin in patients with periodontitis and diabetes." (PMID 39109771, 2024). "As such, in our ApoE KO mouse model, we found an upregulation of TNFα and IL-6 in dyslipidemic mice exacerbated by diabetes." (PMID 38390337, 2024). "The final predictors included in the model were age, diabetes, chronic kidney disease, vaccination status, interleukin-6, procalcitonin, leukocytes, lymphocytes, and D-dimer." (PMID 38822405, 2024). "Many early findings have identified the proinflammatory effect of NF-κB, tumor necrosis factor-α (TNF-α), and interleukin-6 (IL-6) on endothelial dysfunction in diabetes." (PMID 38645427, 2024). "In this context, several lines of evidence suggested a pathogenetic role of IL-6 in diabetes and DKD." (PMID 39723211, 2024). "Due to its various functions in regulating glucose balance, IL-6 is a compelling focus in diabetes research." (PMID 39280507, 2024).
diabetes (continued). "The AKI prediction model comprised diabetes mellitus, preoperative serum IL-6 levels and cardiopulmonary bypass time." (PMID 39199217, 2024). "Combining the administration of the two hydrogels in the PDCM group led to a significant decrease in IL-6 and TNF-α cytokines at the gingival level in periodontal disease associated with diabetes mellitus." (PMID 39062018, 2024). "The model composed of diabetes and atrial fibrillation and IL-6 with lymphocyte count revealed the highest value for 1-year mortality risk prediction." (PMID 38982355, 2024). "We determined that diabetes mellitus (OR = 3.305), high CRP (OR = 1.002), and high plasma IL-6 (OR = 1.045) were independent risk factors for ARDS-associated hypoactive delirium." (PMID 38523173, 2024). "Diabetes mellitus positively influenced TLR-2 expression on macrophages but adversely affected IL-6 and TNF-α levels." (PMID 39456722, 2024). "The following variables were shown to be clinically important factors and were included in the final model: the number of pack-years, plasma resistin concentrations, hs-CRP, plasma IL-6 concentrations, eGFR, and the presence of diabetes." (PMID 39635208, 2024). "Individuals with diabetes exhibit elevated levels of IL-6, TNF-α, and nesfatin-1, indicating a link betweeninflammation, glucose dysregulation, and diabetes advancement." (PMID 39132231, 2024). "Consistently, in this study, ASCVD patients had an elevated proportion of comorbid diabetes, significantly higher inflammatory markers IL‐6, CRP, and remarkably lower lymphocyte count, lymphocyte percentage and neutralizing antibodies." (PMID 38884329, 2024). "Low platelet count, presence of diabetes mellitus and high interleukin 6 levels were independent factors of lower TSAT." (PMID 39308920, 2024). "A diabetes-induced upregulation in IL-1, IL-6, Tnf-α, and Tgf-β was observed in both the PRAT and the MAT." (PMID 38069331, 2023). "The administration of cMDSCs propagated from GM-CSF, IL-6, and IL-1β cytokines prolonged the diabetes-free survival of diabetic mice by way of inhibition of activated T cells." (PMID 37296628, 2023). "We performed a randomized crossover trial to investigate the impact of daily consumption of InsP6 on serum levels of adiponectin, TNF-alpha, IL-6, and IL-1beta in patients with type 2 diabetes mellitus (T2DM; n = 39)." (PMID 36854678, 2023). "The result of this study indicates that scaling and root planing is effective in glycemic control and also has a role to play regarding salivary IL-6 in periodontal health and type 2 diabetes mellitus with chronic periodontitis." (PMID 37854742, 2023). "The influence of diabetes on the cytokine profile in our OSA patients was shown by increased levels of IL-6 and TRAIL." (PMID 36769452, 2023). "The highest cumulative event rate was observed in patients with diabetes with high IL-6 levels (20.3%)." (PMID 36675812, 2023). "Various other clinical characteristics such as mean age, percent women, body mass index, smoking status, history of diabetes, history of cardiovascular disease, and mean IL6 and CRP levels were also investigated by sRAGE levels." (PMID 37198231, 2023). "Most previous studies on the association of protein supplementation with proinflammatory cytokines have focused on healthy older adults, diabetics, or sarcopenic obesity, where the impact on IL-6 and TNF-α has been variable." (PMID 37644985, 2023). "This study showed that 12 weeks of oral treatment of TRF in rats with STZ-induced diabetes reduces expression of the markers of retinal inflammation including IL-1β, IL-6, TNF-α, IFN-γ, MCP-1, and iNOS." (PMID 37268913, 2023). "The administration of a methanolic extract of MO to Wistar rats with nephrotoxicity induced by diabetes restored the typical unfavourable side effects caused by streptozotocin (STZ) by lessening the presence of TNF-α and IL-6." (PMID 37570837, 2023).
diabetes (continued). "Inflammatory biomarkers, such as C-reactive protein (CRP) and interleukin-6 (IL-6), serve as indicators of the inflammatory state and have the potential to aid in predicting the likelihood of developing diabetes and experiencing cardiovascular complications." (PMID 37724233, 2023). "Aging and some comorbidities, such as diabetes, are low-grade inflammatory states with increased levels of proinflammatory markers (IL-6 and TNF-α)." (PMID 37003999, 2023). "With regard to cutaneous wound healing, IL-6 plays a pivotal role, similar to pre-existing diabetes." (PMID 36675638, 2023). "Three of these—IL-6, NFkB and PIK3CG—have been linked with peri-implantitis and diabetes mellitus type 2." (PMID 37232785, 2023). "Reduction in clinical inflammation and salivary IL-6 levels help in the metabolic control of diabetes." (PMID 37854742, 2023). "Treatment with quercetin largely inhibited SARS-CoV-2 N protein-induced F4/80+ macrophages infiltrating the diabetic kidney and greatly suppressed the mRNA expression of IL-6, TNF-α, and MCP-1 while increasing the expression of IL-4 and IL-10 mRNA levels." (PMID 38022581, 2023). "In the case of WAT inflammation, macrophages build up and produce inflammatory cytokines, such as TNF-α and interleukin-6 (IL-6), that disturb the insulin receptors of adipocytes, leading to reduced insulin sensitivity and diabetes." (PMID 39872245, 2023). "Mohamad Akbari’s group and Dan Qu’s group both considered elevated levels of interleukin 6 (IL-6) to be an independent predictor of diabetes." (PMID 38027115, 2023). "Another pro-inflammatory cytokine that exhibits neurotrophic activity, IL-6, contributes to neuronal development and predicts the progression of diabetes, and is also a sensitive marker for diabetic nephropathy." (PMID 37629665, 2023). "C-reactive protein (CRP) and interleukin-6 (IL-6) are significantly elevated in patients with diabetes, hypertension, and the metabolic syndrome." (PMID 37894687, 2023). "DEXA+ MET association reduced the inflammation profile of TNF-α and IL-6, results explained by the anti-inflammatory role of MET in diabetes mellitus." (PMID 37894792, 2023). "In patients with diabetes mellitus, there are also impaired T-cell function and increased concentrations of interleukin-6." (PMID 37397011, 2023). "IL-6 also interacts with the hypothalamic-pituitary-adrenal axis, resulting in increased insulin sensitivity that triggers diabetes, as well as increased BMI and blood pressure that lead to hypertension." (PMID 37900560, 2023). "When SGLT2 inhibitors were provided, the same group showed diabetes-associated increases in inflammation-suppressed NLRP3 inflammasome activity as well as lower mRNA levels of ASC, IL-6, IL-1b, TNF-a, and caspase-1." (PMID 37566054, 2023). "Diabetes is associated with chronic inflammation, which is mainly due to increased plasma concentrations of C-reactive protein (CRP), fibrinogen, interleukin-6 (IL-6), interleukin-1 (IL-1), and TNF α." (PMID 37974282, 2023). "Diabetes condition increases inflammation, this is in accordance with our study, which showed an increase in the expression of IL-6 and TNF-a in inflammatory cells." (PMID 36599453, 2023). "It has been shown that the Lachnospiraceae NK4A136 group is correlated with elevated levels of intestinal IL-17 and IL-6 in mice with diabetes mellitus, resulting in intestinal inflammation." (PMID 36902001, 2023). "In diabetes, IL-6 inhibits the viability and apoptosis of pancreatic beta-cells via modulation of microRNA-22 in the JAK/STAT signaling pathway." (PMID 36597092, 2023). "According to a recent study, ambulatory elderly patients with heart failure and elevated IL-6 more frequently presented with atrial fibrillation, hypercholesterolemia, diabetes mellitus, anemia, and renal dysfunction." (PMID 37373960, 2023). "Diabetes itself leads to increased cytokine production, including interleukin (IL)-1, IL-6, IL-8, and tumor necrosis factor-α (TNF-α)." (PMID 37834356, 2023).
diabetes (continued). "However, it is still unclear whether IL-6 is causing or contributing to diabetes." (PMID 37894687, 2023). "Eight risk factors (1 kg higher body weight, diabetes, education, hypertension, hypercholesterolemia, pre-operative C-reactive protein (CRP), pre-operative interleukin 6, pre-operative S100b) were detected in a mix of surgery types." (PMID 36836145, 2023). "Total amounts of TGF-β, MIP-1α, IL-6, IL-2, and IL-17 were significantly increased in the periodontally healthy sites of diabetes patients (p < 0.05), compared to those of the controls." (PMID 37835794, 2023). "Blackberry juice significantly (p < 0.05) reduced increased hepatic TNF-α and IL-6 by about 65% and 69%, respectively, in rats with diabetes in comparison to only rats with diabetes." (PMID 37280499, 2023). "According to epidemiology, patients with diabetes mellitus (DM), hypertension, atherosclerosis, and cardiovascular events had increased levels of IL-6 and TNF-a." (PMID 37522129, 2023). "The periapical inflammation of LPS-induced apical periodontitis in diabetes mellitus rats increased macrophages' expression of IL-6 at 42 days and TNF-a at 28 days." (PMID 36599453, 2023). "Allium Sativum plays a role in the treatment of diabetes by enhancing the gene expression of caspase 3 and caspase 9, reducing IL-1β, IL-6, and TNF-α level and increasing IFN-γ in vitro and in vivo." (PMID 37240430, 2023). "In our study, diabetes elevated the prefrontal cortex and hippocampal gene expression of NfκB, IL-1β, and IL6, as well as the immunoexpression of TNF-α and GFAP, which are considered indicators of astrocyte activation." (PMID 38105928, 2023). "This nomogram included various factors such as chronic renal diseases, diabetes, systolic blood pressure, interleukin-6 (IL-6), fibrinogen, and BUN (AUC: 0.840, 95% CI: 0.809–0.872)." (PMID 38259861, 2023). "Retinal IL-1 and IL-6 production in the T1 diabetes mellitus group was significantly increased compared to that in the T2 diabetes mellitus group." (PMID 36658547, 2023). "Empagliflozin substantially decreased renal production of pro-inflammatory cytokines and chemokines (including tumor necrosis factor (TNF)), urine indicators of kidney inflammation (such as IL-6), and apoptosis in a diabetes-induced rat model." (PMID 37047011, 2023). "In contrast, employing curcumin-loaded nanofibers improved wound healing in an STZ-induced diabetes model and decreased the quantity of IL-6 produced in vitro from lipopolysaccharide-activated macrophages." (PMID 37575261, 2023). "gingivaliscan produce apical periodontitis in diabetes mellitus rats in anin vivomodel, and affect the expression of IL-6 and TNF-a." (PMID 36599453, 2023). "In contrast, some infection markers such as IL-6, and C-reactive protein increase in people who report prolonged sleep, which accelerates the progression of diabetes and its complications." (PMID 36998281, 2023). "AGEs, substances in the blood of people with diabetes, also stimulate cells to express inflammatory cytokines such as IL-6." (PMID 36643585, 2023). "The deletion of IL-33 enhanced diabetes-induced retinal inflammation, evidenced by upregulated pro-inflammatory cytokine expression (Ccl2, Il1b, Il6, Tnf, Tgfb and Inos), sustained gliosis and microglia activation." (PMID 37671525, 2023). "Increased levels of CRP and IL-6 have previously been associated with an elevated risk of CVD and diabetes." (PMID 37388641, 2023). "In this regard, we performed a subgroup analysis of patients according to the presence of diabetes and plasma IL-6 levels." (PMID 36675812, 2023). "The endpoints for the first one were CRP, TAC, MDA, NO, and GSH among individuals with T2DM, while the studied outcomes for the other one were TNF-α, CRP, IL-6, and NO among subjects with diabetes." (PMID 36239789, 2023). "Previous studies documented that, in both diabetes and non-diabetes, markers of inflammation such as C-reactive protein and IL-6 are upregulated after acute hypoglycemia." (PMID 37367911, 2023).